XAF1 (XIAP associated factor 1)
Diseases named in the same sentence as XAF1 in open-access papers (continued):
Sharing a sentence is not in itself a finding about the gene and the disease.
tumor (continued). "Moreover, some researchers have recently indicated the effect of XAF1 combination with these factors on inhibition of tumour growth in vivo and demonstrated that XAF1 can hinder tumour progression and promote outright regression in combination with TRAIL." (PMID 21143993, 2010). "Low XAF1 expression was significantly related to tumour progression." (PMID 19664236, 2009). "XAF1 expression was correlated to clinico-pathological tumour features and prognosis." (PMID 19664236, 2009). "Our results have shown that expression status of XAF1 is associated with the apoptotic sensitivity to ER stress, suggesting that loss or downregulation of XAF1 by promoter hypermethylation may result in GRP78 elevation, thereby enhancing tumor cell resistance to ER stress." (PMID 35902580, 2022). "Furthermore, increased XAF1 expression in resistant cell lines coupled with the inverse correlation of XAF1 expression with GBM survival, suggested that XAF1 could contribute to an aggressive phenotype in GBM which is paradoxical to its tumor suppressor role." (PMID 31575897, 2019). "Thus, XAF1 methylation might provide an additional prognostic and/or predictive value for this tumor entity." (PMID 28122345, 2017). "Finally, we explored the importance of XAF1 expression in regulating tumor growth." (PMID 27097110, 2016). "In this study, one new finding is that XAF1 could inhibit tumor angiogenesis in HCC." (PMID 24980821, 2014). "In addition, after-surgery negative-to-positive transition of XAF1 methylation in sera strongly associated with tumor recurrence." (PMID 23826230, 2013). "Among 12 recurrent patients, 10 patients displayed negative-to-positive transition in XAF1 methylation status in their sera, the other two showed always positive for XAF1 methylation, suggesting that monitoring of XAF1 methylation in serum may be a good marker for predicting tumor recurrence." (PMID 23826230, 2013). "However, low XAF1 tumour levels may provide survival advantages of neoplastic cells in the presence of various apoptotic triggers and may thus still have a role for tumour progression." (PMID 19664236, 2009). "For instance, indicators associated with the IFN pathway, such as the characteristics of interferon-stimulated genes (ISGs) including MX1, EPSTI1, XAF1, and GBP1, have been correlated with tumor sensitivity to VSV." (PMID 40698086, 2025). "By recruiting TRIM28 to another E3 ligase ZNF313, XAF1 promotes ubiquitination and proteasomal degradation of TRIM28, thereby antagonizing its tumor-promoting activity." (PMID 39532800, 2024). "Several of the genes that demonstrated a putative role as predictive biomarkers are either well-known tumor suppressors (RASSF1, XAF1, ASC/TMS1, ASPP1, DAB2IP) or DNA damage response regulators (SLFN11)." (PMID 39051186, 2024). "The expression of therapeutic genes Smac and XAF1 reduced the drug resistance of tumor cells to DDP and inhibited the growth of tumor." (PMID 37182136, 2023). "Given that loss or reduction of XAF1 expression by aberrant promoter hypermethylation is common in human cancers, our data support that epigenetic silencing of XAF1 is a mechanism leading to abnormal elevation of GRP78 and tumor resistance to ER stress." (PMID 35902580, 2022). "To delineate the role for XAF1 in TMZ therapy, we carried out tumor xenograft assays using U373MG sublines." (PMID 35274103, 2022). "It has been reported that XAF1 interacts with IRF1 and inhibits IRF1 degradation during tumor therapy." (PMID 35972291, 2022). "In tumor cells expressing high O6-methylguanine-DNA methyltransferase (MGMT), XAF1 response to TMZ is debilitated." (PMID 35274103, 2022).
tumor (continued). "XAF1 forms a feedback loop with interferon regulatory factor-1 (IRF-1) and evokes its tumor suppression effect in a highly IRF-1-dependent fashion." (PMID 35902580, 2022). "It was reported that Ras/MEK activation increases tumor resistance to antiviral effects of IFNs by downregulating IRF-1 and that XAF1 transcription is repressed by Ras/MEK35–37." (PMID 30042418, 2018). "Collectively, these demonstrate that XAF1 modulates IRF-1 function to stimulate and repress transcription of proapoptotic and tumor-promoting genes, respectively, thereby provoking its tumor suppressive function." (PMID 30042418, 2018). "Consistently, XAF1 and IRF-1 decreased the colony-forming ability of tumor cells in a highly IRF-1- and XAF1-dependent manner, respectively." (PMID 30042418, 2018). "In the present study, we demonstrate that XAF1 forms a feedback loop with IRF-1 under stressful conditions and evokes its tumor suppression effect in a highly IRF-1-dependent fashion." (PMID 30042418, 2018). "Having confirmed the biological relevance of the methylation in the three CpGs analyzed, for XAF1 mRNA and protein expression, we evaluated the XAF1 status in 80 HGG tumor samples." (PMID 28122345, 2017). "By adopting this method, we analyzed the CpG methylation in a distinct promoter region of XAF1 in HGG cell lines and in 80 formalin-fixed, paraffin-embedded (FFPE) tumor samples." (PMID 28122345, 2017). "In recent years, XAF1 being a potent antagonist of XIAP, has been studied with interest for its involvement in tumor suppression." (PMID 27097110, 2016). "However, whether XAF1 inhibits tumor angiogenesis remains unknown." (PMID 24980821, 2014). "Therefore, one can speculate that both, the failure of IFN to induce XAF1 expression in IFN-resistant tumour cells as well as an abnormal reduction of XAF1 protein expression, may contribute to the poor response rates of ccRCC patients to IFN-based immunotherapy." (PMID 19664236, 2009). "The down regulation of XAF1 and/or Smac/DIABLO has been confirmed in a variety of cancer cells and tumor tissues." (PMID 19397802, 2009). "This indicates XAF1 not only to constitute an ISG, but also to mediate the anti-tumour effects of IFN." (PMID 19664236, 2009). "Wound healing and Matrigel assays revealed that IRF-1 and XAF1 strongly suppresses TNF-induced tumor cell migration and invasion and this effect is abrogated by depletion of XAF1 and IRF-1, respectively, indicating TNF-driven tumor malignancy is impaired by the IRF-1−XAF1 interplay." (PMID 30042418, 2018). "Moreover, 14 of 18 (77.8%) low XAF1 tumors and 14 of 20 (70%) low IRF-1 tumors displayed low IRF-1 and XAF1, respectively, indicating that XAF1 and IRF-1 levels correlate tightly in both normal and tumor tissues." (PMID 30042418, 2018). "A total of 26 patients (32.5%) showed a methylated XAF1 promoter in the tumor tissue analyzed with no gender prevalence." (PMID 28122345, 2017). "We further investigated the effect of XAF1 tumor angiogenesis in vivo, and determined the expression of PECAM-1/CD31, a well-established endothelial cell marker in tumor tissues treated with Ad5/F35-XAF1 and Ad5/F35-Ctrl." (PMID 24980821, 2014).
tumor (continued). "We found that XAF1 could induce apoptosis and inhibit VEGF expression, tumor angiogenesis and tumor growth." (PMID 24980821, 2014). "XIAP/XAF1 ratio was significantly higher in tumor than in non-neoplastic parenchyma (FC = 3.02, p < 0.001)." (PMID 19397802, 2009). "In this context it has recently been shown that IFN-treatment of various tumour cell lines lead to a strong up-regulation of XAF1 mRNA but did not affect protein expression." (PMID 19664236, 2009). "In multivariable Cox regression analysis XAF1 expression did not provide independent prognostic information, whereas the conventional prognosticators, e.g. tumour stage, grade and the metastatic status at time of surgery, maintained their prognostic value." (PMID 19664236, 2009). "However, in certain tumor cells with no aberrant promoter hypermethylation, XAF1 protein is hardly detectable, indicating the post-transcriptional inactivation of XAF1." (PMID 39532800, 2024). "Patients with relatively higher XAF1 expression had a markedly lower long-term survival suggesting that XAF1 might not actually play in tumor suppressive or an apoptosis promoting role in GBM as is the case in other cancers." (PMID 31575897, 2019). "Therefore, XAF1 methylation does not represent an independent prognostic marker in this particular tumor entity but provides a surrogate marker of IDH1 and probably IDH2 mutations." (PMID 28122345, 2017). "Moreover, we detected high frequency of XAF1 methylation (69.8%, 141 out of 202) in the sera DNAs from the same patients, while the sera DNAs from 88 non-tumor controls were negative for XAF1 methylation." (PMID 23826230, 2013). "Interestingly, we found that XAF1 is a novel substrate of TRIM28 and that EGF-induced TRIM28 protects tumor cells from etoposide-induced apoptosis more significantly in XAF1+/+ versus XAF1−/− cells, indicating that TRIM28 exerts anti-apoptotic effect in a highly XAF1-dependent fashion." (PMID 39532800, 2024). "Collectively, this study identifies XAF1 as a novel antagonist of TRIM28 and the presence of mutual antagonism between XAF1 and TRIM28, raising the possibility that the restoration of balanced XAF1-TRIM28 interplay could be an attractive avenue for the therapeutic intervention of tumor progression." (PMID 39532800, 2024). "However, the nuclear translocation of XIAP is not recognized in certain tumor cells undergoing XAF1-driven apoptosis and that XAF1 has comparable proapoptotic activity in XIAP−/− and XIAP+/+ cells, indicating that XAF1 can promote apoptosis through the XIAP-independent mechanisms." (PMID 30042418, 2018). "Furthermore, XAF1 has been identified as an interferon-stimulated gene (ISG), which's expression is up-regulated by the exposure to IFN-α and IFN-β, resulting in a sensitization of various tumour cell lines to tumour necrosis factor-related apoptosis inducing ligand (TRAIL)-induced apoptosis." (PMID 19664236, 2009). "Moreover, XAF1 expression is low or absent in several tumor cell lines." (PMID 19397802, 2009). "However, the expression of Apaf-1, PUMA and XAF1 expression did not correlate with tumor thickness." (PMID 16755297, 2006). "H&E staining demonstrated that tumor necrosis induced by IFN-γ treatment was decreased in the BRD7-depleted group and that IFN-γ-induced XAF1 expression was not shown in BRD7-depleted tumors." (PMID 26802028, 2016).
cancer (54 papers, 2007 to 2025). A tumor composed of atypical neoplastic, often pleomorphic cells that invade other tissues. "The loss of XAF1 expression is associated with advanced cancer stages, highlighting its role in tumor progression." (PMID 40558276, 2025). "X-linked inhibitor of apoptosis-associated factor 1 (XAF1) is a stress-inducible pro-apoptotic protein that is commonly inactivated in multiple human cancers." (PMID 39532800, 2024). "Epigenetic inactivation of XAF1 due to aberrant promoter hypermethylation is observed in a broad range of human cancers and associates with the stage and grade of many tumors." (PMID 35902580, 2022). "A recent integrated analysis of data from a PTEN loss-driven mouse model and cancer patients demonstrated that XAF1 downregulation is a predictive and actionable signature of castration-resistant prostate cancer." (PMID 30042418, 2018). "Loss of XAF1 expression through promoter methylation has been implicated in the process of tumorigenesis in a variety of cancers." (PMID 17376236, 2007). "This approach accounts for the phenotypic variability of cancer within families, particularly regarding the p.R337H variant, which is frequently found in conjunction with the XAF1 p.E134* variant in about 70% of cases in Paraná, complicating the understanding of cancer risk." (PMID 40558276, 2025). "In addition, previous studies suggested that allelic loss of the XAF1 gene is prevalent in cancer cell lines." (PMID 24874286, 2014). "Loss of XAF1 has been observed in a variety of cancer cell lines and human cancers." (PMID 21143993, 2010). "The loss of XAF1 is associated with malignant tumor progression in a variety of cancers." (PMID 17376236, 2007). "It is therefore predicted that methods that enhance XAF1 levels could increase apoptotic susceptibility and provide an additional strategy for cancer therapy." (PMID 17376236, 2007). "Moreover, the upregulation level of MTF1 and the downregulation level of XAF1 were investigated in various kinds of tumors, and the alteration of MTF1-XAF1 could cause cancer resistance of apoptosis induced by heavy metal." (PMID 37380924, 2023). "In a study by Chen’s team, the methylation profile of XAF1 was meticulously quantified in both primary EC tissues and their adjacent, cancer-free counterparts." (PMID 40718833, 2025). "MAP1LC3A, AQP1, and AP1S1 were consistently amplified across cancer types whilst XAF1, CASP3, and SNCA exhibited copy deletions." (PMID 38642129, 2024). "XAF1 is expressed ubiquitously in normal tissues but markedly downregulated or undetectable in a substantial faction of cancer cell lines and primary tumors due to aberrant promoter hypermethylation." (PMID 39532800, 2024). "Epigenetic alteration of XAF1 is frequent in cell lines and primary tumors and contributes to cancer cell growth." (PMID 35274103, 2022).
cancer (continued). "XAF1 expression is associated with overall survival of TMZ treatment patients, particularly with low MGMT cancer." (PMID 35274103, 2022). "XAF1 exists in several isoforms; however, their function and prognostic significance in cancer remain an open question." (PMID 33734579, 2021). "Upregulation of XAF1 expression was observed to suppress cancer cell growth and increase cell sensitivity to chemotherapy." (PMID 33747900, 2021). "Along with XAF1, we discovered the up-regulation of a subset of genes with the capacity to inhibit cell proliferation and to stimulate cancer cells to undergo apoptosis (IRFs, IFIT1-3, ISG12a, IFITM and the OAS family members)." (PMID 28184177, 2017). "For example, XAF1 has been shown to inhibit proliferation and to induce the apoptosis of cancer cells as it negatively regulates the caspase-inhibiting activity of XIAP." (PMID 28184177, 2017). "XAF1 is expressed ubiquitously in all healthy adult and fetal tissues, but is lost or reduced in a variety of cancer cell lines because of the aberrant promoter hypermethylation of its gene." (PMID 26802028, 2016). "In the present paper, we demonstrate that in cancer cells, CTCF is unable to associate with its cognate DNA-binding site in the XAF1 promoter if it is methylated, thus effectively rendering it unresponsive to well-known activators." (PMID 26443201, 2015). "DNA demethylating agents induce transcriptional reactivation of XAF1, sensitizing cancer cells to therapy." (PMID 26443201, 2015). "Our results demonstrate that XAF1 inhibits HCC cancer growth via suppressing VEGF expression and angiogenesis." (PMID 24980821, 2014). "The mRNA and protein expressions of XAF1 were determined in 3 HCC cancer cell lines SMMC-7721, Bel-7404 and Hep G2, as well as 30 primary HCC cancer and paired non-HCC tissues." (PMID 24980821, 2014). "The hypermethylation frequency of XAF1 in cancers is significantly higher than that in PCHNTs and non-cancer controls (all p<0.0001)." (PMID 23826230, 2013). "XAF1 is expressed ubiquitously in all normal cells, in contrast to extremely low or undetectable levels in several cancer cells." (PMID 23685456, 2013). "Dysfunction of XAF1 has been reported in several human cancers probably through promoter methylation, suggesting its importance in tumorigenesis." (PMID 23826230, 2013). "XAF1 can dramatically sensitize cancer cells to apoptotic triggers such as TRAIL, etoposide treatments 5-fluorouracil, H2O2, c-irradiation, ultraviolet, and tumour necrosis factor-α, which are independent of its interaction with XIAP." (PMID 21143993, 2010). "A number of studies have shown that XAF1 can sensitize cancer cells to TRAIL, TNF-α, Fas, IFN-β and MEK inhibitor-induced apoptosis in vitro." (PMID 21143993, 2010). "Likely, up-regulation of XAF1 mediated by somatostatin and Octreotide triggers cancer cell apoptosis." (PMID 21143993, 2010). "XAF1 is ubiquitously expressed in normal human tissues, but at comparably low or undetectable levels in numerous cancer cell lines with high XIAP expression on the other hand." (PMID 19664236, 2009). "Among the multitude of genes that are modulated by IFN and can potentially enhance cell sensitivity to TRAIL-induced apoptosis, we show that xaf1 alone is important and essential in mediating susceptibility to TRAIL-induced apoptosis in cancer cells." (PMID 17376236, 2007).